CD4 (CD4 molecule)
Diseases named in the same sentence as CD4 in open-access papers (continued):
Sharing a sentence is not in itself a finding about the gene and the disease.
infection (continued). "In addition, the expression of IFN-γ, TNF-α, CD69, and IFN-γ mRNA in the lung CD4+ T cells and IFN-γ in spleen CD4+ T cells significantly elevated after infection in WT mice (p = 0.00012, 0.0172, 0.0038, 0.00562, and 0.0117, respectively)." (PMID 33628846, 2021). "Still, based on sCD4, CD4-IgG2 (PRO 542), comprised of the D1D2 domain of CD4, showed high affinity, and CD4-IgG2 could neutralize more primary isolates than sCD4 alone, and it could protect the hu-PBL-SCID mouse from infection of primary HIV-1 isolates." (PMID 33807292, 2021). "Several previous studies have used transcriptomics to evaluate the cellular responses to human immunodeficiency virus type 1 (HIV-1) infection; however, none have examined events in primary CD4+ T cells during the first 24 h of infection." (PMID 34154423, 2021). "(C) Spike-specific CD4+ T cells expressing the homeostatic proliferation marker CD127 and lacking expression of the terminal differentiation marker CD57 are more frequent in vaccinated convalescent than vaccinated infection-naïve individuals." (PMID 34636722, 2021). "Our data suggest that CD4+ T-cell reactivity is not a suitable measure of past infection and does not reliably indicate protection from infection in naive individuals." (PMID 34795668, 2021). "Our results showed that platelet-CD4+ T cell aggregates have a higher expression of CD45RO than their counterparts, which indicates their potential capability of binding to platelets and infection by HIV-1." (PMID 34987521, 2021). "The HIV+/METH− and HIV+/METH+ groups did not significantly differ on infection duration (ηp2 = 0.02), current CD4 count (ηp2 = 0.03), or nadir CD4 count (ηp2 = 0.01)." (PMID 34960745, 2021). "While there are a number of prior studies for HIV-1, few have been conducted with primary CD4+ T cells, and none of these have interrogated the first 24 h of infection." (PMID 34154423, 2021). "Briefly, activated CD4+ T cells from healthy donors were infected with a full length, replication competent HIV-GFP reporter virus and RT inhibitors were added beginning 72hr post infection." (PMID 33465149, 2021). "As expected, CD4 counts decreased following cyclophosphamide administration with no documented clinical infection." (PMID 34721269, 2021). "The expression of PD-1 on CD4+ or activated CD4+ T cells was significantly increased on day 5 and day 10 p.i. after lethal P.y17XL and non-lethal P.y17XNL infections." (PMID 33430765, 2021). "First, we investigated the number of T cell subtypes recruited into the CNS and observed a significant reduction of CD8+ T effector memory (Tem) cells but not CD4+ T effector cells in brains of TKO mice in the chronic phase of infection (F’)." (PMID 33968021, 2021). "Soluble CD4 failed to block infection by HIV-1 clinical isolates, dampening the initial enthusiasm for the decoy-receptor strategy." (PMID 33922579, 2021). "Deletion of LEC MHC-II did not impede reactivation of CD4+ TRM cells nor affected rapid clearance of Spn and as such, these infections mimic homeostatic nonlethal inhalation of microbes to which adult lungs would already possess CD4+ TRM cells." (PMID 34611166, 2021). "Furthermore, the baseline CD4 count among the diagnosed PLHIV is important to determine the approximate time of HIV infection to understand whether there is a delay in case of diagnosis since infection and appropriate interventions can be taken to enhance early diagnosis." (PMID 33945664, 2021). "According to this, low risk patients are GvHD-free, off IST, do not experience recurrent infections and CD4 counts are >200/μL." (PMID 34395344, 2021). "Acute CD4+ T-cell depletion is substantial in progressive, nonprogressive and controlled infections." (PMID 34367156, 2021). "In 1998, kidney epithelial cells cultured from the urine of children with HIVAN were used for the first time to demonstrate that HIV-1 isolates derived from children with HIVAN can induce a low-level productive infection in the absence of CD4." (PMID 33044676, 2021).
infection (continued). "CD4/viral counts require interval evaluation, as this may impact survival, and if mortality was related to PH or complications due to HIV (i.e. infection)." (PMID 33621231, 2021). "This required simultaneous measurement of circulating antibodies, memory B cells, CD8+ T cells, and CD4+ T cells specific for SARS-CoV-2, in a group of subjects with a full range of disease, and distributed from short time points after infection out to 8 months later." (PMID 33408181, 2021). "Fibroblasts are abundant in these tissues, and although not susceptible to infection, can potently enhance HIV infection of CD4+ T cells." (PMID 33976386, 2021). "Peptide vaccination may prime CD4+ and CD8+ T cells, and generate immune memory that is recalled upon infection, to support protective humoral and cellular mechanisms of immunity." (PMID 33986292, 2021). "Given the early IFN-γ response at day 1 of infection, NK (TcRβ- NK1.1+), NKT (TcRβ+ CD1d tetramer+), CD4+ T (TcRβ+ CD4+) and CD8+ T (TcRβ+ CD8+) cell populations were examined in the liver and spleen of MIL-SPpyRE9/DsRed and MIL-RPpyRE9/DsRed infected C57Bl/6 mice." (PMID 34292975, 2021). "Importantly, the anti-mycobacterial effect on ΔhisD was completely reversed upon incubation of CD4 T-cell activated primary macrophages with anti-IFN-γ antibodies, suggesting a direct role of IFN-γ in clearing the ΔhisD infection." (PMID 33767335, 2021). "The predicted time delay is in qualitative agreement with the experimental study, where no CD4+ T cells were detected in any lung tissues at four days post-infection." (PMID 34343169, 2021). "Several studies have documented the significance of antiviral CD4+ as well as CD8+ T cells in the control of infection in HIV-1 non-progressors and HIV-2 slow progressors." (PMID 33936106, 2021). "The nonprogressive infection of African nonhuman primate SIV hosts is characterized by partial mucosal CD4+ T-cell restoration, despite high viral replication." (PMID 34367156, 2021). "Three weeks post‐infection, the mean CD8+/CD4+ T‐cell ratios in mice infected with EBV S457A/T465V (0.99) were significantly higher than in EBV wt (0.37)‐infected mice, while CD8+/CD4+ T‐cell ratios of EBV wt‐infected animals increased later, at 4 weeks post‐infection." (PMID 34605140, 2021). "CD4+ T cells are crucial in cytomegalovirus (CMV) infection, but their role in infection remains unclear." (PMID 34950144, 2021). "Infection with HIV also leads to the death of both infected and uninfected helper CD4+ T cells." (PMID 34578331, 2021). "We cannot rule out new infection of CD4+ T cells that remained in the co-cultures after three rounds of washing." (PMID 33594125, 2021). "MHV68 infection of mice lacking CD4 T cells leads to uncontrolled MHV68 reactivation in mice and eventual death." (PMID 34586873, 2021). "Thus, an early and consistent TNF-α response was observed in the low dose group while a delayed but a more robust TNF-α response in both Mtb-specific CD4+ and CD8+T cells was observed in the high infection dose." (PMID 34484203, 2021). "In contrast to other studies, CD4 levels at both recruitment (<6 months post infection) and the time of bnAb measurement did not negatively correlate with neutralization score." (PMID 34127581, 2021). "Similar initial responses may be detected early in persisting infections, but HCV-specific CD4+ T cell populations soon decline and become nearly undetectable." (PMID 34372558, 2021). "Importantly, both CD4+ and CD8+ T cells with a cytotoxic phenotype were strongly induced ~1 week after infection, suggesting that both types of T cells play a role in the lysis of infected cells." (PMID 33398113, 2021). "An alternative explanation is that a portion of the memory CD4 T cells are not reactivated by antigen immunisations and therefore remain blind to the tolerogenic signals and free to respond to the infection." (PMID 32931017, 2021). "Both CD4+ and CD8+ T-cells are involved in anti-viral immunity and during infection." (PMID 34106915, 2021).
infection (continued). "We found that marginally more SARS-CoV-2-specific CD4+ T-cells were induced three months after vaccination than after infection, although these differences were not significant (mean 0.245% ± 0.063 versus 0.136% ± 0.045)." (PMID 34960185, 2021). "Additionally, mice from CC-RIX lines with LID upon infection also had an increased circulating fraction and number of splenic CD8 and CD4 T cells that express IL-17 upon stimulation." (PMID 33513210, 2021). "Resistance to re-infection also depends heavily on CD4+ T cells, IFN-γ and/or IL-12, highlighting the overall importance of T helper 1 (Th1) immunity in controlling this intracellular pathogen during primary and secondary infections." (PMID 34695149, 2021). "There were modest but statistically significant differences in the prevalence of females and recent infection cases among infecting subtypes, but not in median age, plasma viral load or CD4 count." (PMID 34305873, 2021). "Although overall CD4 depletion and restoration kinetics in the colon were similar in SIV and SHIV-infected animals, the magnitude and impact on certain CD4 cell types were distinct between the two infections." (PMID 34452474, 2021). "To this end, we isolated CD4+ T cells from healthy donors and then transfected them with antagomiR-31 or antagoNC, followed by 72-hr stimulation with anti-CD3/CD28 antibodies before infection with HIV-1 at a multiplicity of infection (MOI) of 0.01." (PMID 34804062, 2021). "However, a great proportion of CD4+ T-cells in MLN remained as single CCR4+ after 30 days (32.68 ± 1.11%) and 60 days of infection (33.44 ± 13.63%)." (PMID 34685494, 2021). "HIV infection affects the functions and metabolism of T cells, which may determine the fate of patients; however, the specific pathways activated in different T-cell subtypes (CD4+ and CD8+ T cells) at different stages of infection remain unclear." (PMID 34603402, 2021). "Low titer CC-RIX mice with superior virologic containment at day 2 post-infection had a higher mean frequency of CD44+ CD4 and CD8 T cells in the spleen prior to infection, in addition to an increased proportion of CD4 T cells that express Ki67, which signals recent proliferation." (PMID 33513210, 2021). "There is a paucity of studies measuring pre-existing CD4+ T cell immunity in a cohort of non-infected individuals and then following their infection rate over time." (PMID 34795668, 2021). "Our study results showed that USP12 activated CD4+ T cell signaling, and targeting USP12 might help develop therapeutic interventions for treating inflammatory diseases or pathogen infections." (PMID 33941870, 2021). "Moreover, compared with the normal level T lymphocyte group, more infection events occurred in the low CD3+, CD4+ and CD4+/CD8+ ratio T lymphocyte group except for the low CD8+ T lymphocyte group." (PMID 34568395, 2021). "Besides, we also detected the expressions of T help cell differentiation-related transcription factors including TBX21 (T-bet), GATA3, and Foxp3 between CD4+CD8low+ double-positive T cells and CD8+ single-positive T cells after ALV-J infection." (PMID 34858872, 2021). "We performed phenotypic and transcriptomic characterization of CD32+CD4+ T cells at different stages of infection in lymphoid and non-lymphoid tissues (LN, spleen, jejunum, ileum, liver, blood)." (PMID 34220857, 2021). "Interestingly, IL-10+CD4+ and IL-10+CD8+ heart T cells were increased in mice treated with anti-IL-2 mAb during this phase of the infection compared to control infected rat IgG-treated mice." (PMID 34869064, 2021). "A T-cell targeting vaccine composed of conserved epitopes may provide rapid, effective, and long-term immunity at sites of infection through the generation of tissue resident memory CD8+ T cells, as well as memory CD4+ T cells that support antibody responses." (PMID 33986292, 2021).
infection (continued). "Additionally, in mildly symptomatic patients, CD4+ and CD8+ T-cells proliferated in response to the S protein significantly more than to the M protein (p = 0.020) at the early time point post infection." (PMID 34835067, 2021). "Prior to M.tb infection we detected robust levels of M.tb lysate-specific CD4 T cells with relatively high FS and PFS, which increased to even higher levels upon infection (recent QFT+) that were in a similar range to those detected in persistent QFT+ individuals." (PMID 33610126, 2021). "Most CD4+ T-cells in the blood, spleen, and MLN of control HIS-NSG mice expressed CC-chemokine receptor 4 (CCR4) without the presence of CCR5 and CXC-chemokine receptor 3 (CXCR3), which were indeed upregulated upon infection." (PMID 34685494, 2021). "Additionally, IL-6 was shown to be important for the generation of Tfh CD4+ T cells (through upregulation of Bcl6) and B cell responses later during LCMV Cl 13 infection." (PMID 34696381, 2021). "CD3+CD4+ T cells, CD3+CD8+ T cells and CD45+CD14+ monocytes were present in reconstituted mice, suggesting that HuPBL-NCG mice harbored the major cellular targets for SFTSV infection." (PMID 33974679, 2021). "However, after infection with reovirus, both the CD8+ and CD4+ T cells had downregulated HVEM, in keeping with previous reports showing the downregulation of HVEM on virus-specific T cells at the acute stage of vaccinia virus infection." (PMID 33665363, 2021). "Both CD4+ and CD8+ T cells infiltrate the brain following the infection of newborn mice." (PMID 34200083, 2021). "In the absence of antiretroviral therapy, infection with human immunodeficiency virus type 1 (HIV-1) is characterised by prolonged viremia, progressive CD4+ T cell loss, and persistent immune activation that ultimately leads to compromised immune responses." (PMID 34630420, 2021). "Thus, the percentages of CD4+IFN-γ+ and CD4+ TNF-α+T cells were significantly lower in the high dose group compared to the low dose group at week 1 post-infection." (PMID 34484203, 2021). "In addition, recovered individuals show persistent alterations in CD4+ and CD8+ T cell memory compartments 6 months after infection." (PMID 33533915, 2021). "CD4+ T cell infection in PB was not strongly correlated with that in CSF, for either gag+ only or env+gag+ cells, in this small sample set." (PMID 34874976, 2021). "The positive effects correlated with increased splenic frequencies of CD8+T effector cells and an increase in the production of IFN-γ and cytolytic molecules (perforin and granzyme) by the CD4+ and CD8+ effector and central memory subsets in response to challenge infection." (PMID 34497271, 2021). "For donor M, for whom we had previously sequenced memory subpopulations before the infection, we were able to identify pre-existing SARS-CoV-2-reactive CD4+ clones in the CM subpopulation 1 year before the infection and a group of CD8+ clones in the pre-infection EM subpopulation." (PMID 33399535, 2021). "IL-10 overexpression early during infection did not, we found, significantly impair the kinetics of CD4+ T cell priming and effector differentiation." (PMID 34554927, 2021). "HIV-1 trans-infection is a dynamic process that involves viral attachment to Siglec-1, internalization within a viral containing compartment (VCC), and viral release to the intercellular space during the formation of DC:CD4+ T cell infectious synapses." (PMID 35055987, 2021). "At day 30 after infection, we confirmed that RAG–/–:B6 and RAG–/–:pMT-10 mice presented similar frequencies of total CD4+ T cells and total M. tuberculosis–specific IFN-γ–producing CD4+ T cells in the lungs." (PMID 34554927, 2021). "Especially, in synergy with CD4+ T lymphocytes, CD8+ T lymphocytes are key to limit T. gondii invasion during acute spreading of T. gondii tachyzoites or to limit the formation of brain cysts in the late stage of infection." (PMID 34595126, 2021).
infection (continued). "SARS-CoV-2 CD4+ and CD8+ T cell responses in infection and vaccination." (PMID 35004764, 2021). "Although CD4+ T cells play a central role in coordinating host defences against P. jirovecii, the inhibition and cytotoxic effects of CD8+ T cells seem to be critical to control and terminate the infection." (PMID 33985440, 2021). "The frequencies of CD4 and CD8 TRM cells increased in the brain during the late stage of infection." (PMID 34587172, 2021). "At both early and late stage of the infection, antigen presentation of rFhCB3 and rFhCL2 resulted in higher stimulation index of CD4+ T cells which was IL-2 mediated, although no statistically significant when compared to uninfected animals." (PMID 34215335, 2021). "Although T cell activation markers such as HLA-DR and CD38 showed a higher expression tendency in the more severe group, especially early after infection (TP1), the difference in the frequency of activated CD4+ and CD8+ T cells between mild and more severely affected patients was not significant." (PMID 34867933, 2021). "Strikingly naive CD4 T cells from neonatal mice had a heightened capacity to phosphorylate STAT5 in response to IL-2, and antibody-mediated immunity can be boosted by removing IL-2 signaling during neonatal infection." (PMID 34665220, 2021). "Although we could not find any significant differences between the percentage of CD4+ and CD8+ cells during the infection, we did observe that they significantly increased in number after 15 dpi." (PMID 34943041, 2021). "The therapeutic potential of transferring HBV immunity initially emerged through clinical reports of CHB patients who cleared the infection after receiving a bone marrow transplant from HBV-immune donors, giving rise to HBV-specific CD4+ and CD8+ T cells as well as B cells." (PMID 34853796, 2021). "Pre-conditioning with supernatant from NT or HAS2KO fSFs did not increase the infection rates of the CD4+ T cells, consistent with soluble factors not being important for fibroblast-mediated enhancement of HIV infection." (PMID 33976386, 2021). "Together, these data indicated that depletion of CD4+ T-cells impaired early CCHFV-specific IgG but did not impair the acute CD8+ T-cell response to the infection in the liver by the criteria measured." (PMID 33572859, 2021). "As expected, since S. tm induces inflammation mainly in the cecum in vivo, IL-17A production from CD3+CD4+ small intestinal LPLs was not altered after infection with S. tm.." (PMID 34566952, 2021). "Here, we show that IL-10 overexpression only before the onset of the T cell response impaired control of M. tuberculosis growth; during chronic infection, IL-10 overexpression reduced the CD4+ T cell response without affecting the outcome of infection." (PMID 34554927, 2021). "After infection, naive antigen-specific CD4+ and CD8+ T cells clonally expand and differentiate into effector cell populations, which further segregate into phenotypically diverse long-lived memory T cell subsets that provide protection upon (re-)infection." (PMID 33458613, 2021). "Within days of exposure, regardless of the route of infection, SIV or HIV reaches the intestinal tract, where marked viral replication, amplification, mutation and massive CD4+ T cell depletion occur." (PMID 34960667, 2021). "IL-1α/β enhances IgM and recruitment of CD4+ T cells at the site of infection but does not contribute to killing the virus-infected cell." (PMID 34696231, 2021). "CD4 T-cell counts correlated inversely with the amounts of proliferated TIGIT+NK (r = −0.63, P = 0.007) and TIGIT−NK cells (r = −0.68, P = 0.003) only in the first month of infection." (PMID 33717085, 2021). "This study also showed that the administration of the HET–KKT combination increased the number of NK cells and T cells, the cytotoxic activity of NK cells, the total number of T cells, and CD4/CD8-positive cells, indicating that the infection protection ability was enhanced." (PMID 34867392, 2021).